LEP (leptin)
Diseases named in the same sentence as LEP in open-access papers (continued):
Sharing a sentence is not in itself a finding about the gene and the disease.
Obesity (continued). "In one of the studies, the authors found a positive association of skinfold thickness (as an indicator of adiposity in neonates) with free leptin (calculated as plasma leptin/soluble leptin receptor) in women with pregestational obesity but negative in non-obese mothers." (PMID 34523036, 2022). "On the other hand, mature adipocytes, a bridge between obesity and GSD, could secrete leptin." (PMID 36506064, 2022). "Circulating leptin levels are increased in patients with obesity, and these individuals may experience leptin resistance; that is, these increased leptin levels no longer promote satiety." (PMID 35610699, 2022). "Similarly, a positive correlation was observed between increased serum leptin and TSH levels in euthyroid obese women; the increased amount of fat in patients with severe obesity could result in an increase in TSH and leptin levels." (PMID 36401211, 2022). "However, in a different study, leptin levels decreased in subjects with overweight or obesity who followed an ADF protocol, but adiponectin levels did not change, nor did other biomarkers of inflammation, including resistin, IL-6, or TNF-α." (PMID 36364915, 2022). "In obesity, serum levels of adiponectin are found in low amounts, unlike leptin." (PMID 35386146, 2022). "Obesity-related hormones, such as leptin and ghrelin, were not involved." (PMID 35966092, 2022). "Since our levels were normalised against standard housekeeping genes the raised levels of circulating leptin in obesity may result from the greater adipocyte number rather than an increase per adipocyte." (PMID 35933445, 2022). "However, clinical (BMI) signs that corroborated with plasma leptin for underweight and obesity exist, and there appear to be no significant polymorphic changes observed in the LEP and LEPR gene." (PMID 35886710, 2022). "However, the paradox exists that in obesity, the leptin levels are increased; despite this, there is no indication or signal of satiety due to a peripheral and/or central resistance to leptin." (PMID 35563589, 2022). "While there may be differences in the adiponectin/leptin relationship with obesity according to sex, no sex-modifying effects were observed in the associations evaluated." (PMID 35204183, 2022). "Although there are no previous studies examining the role of ghrelin, IR, leptin, and adiponectin in self-report eating styles in obesity, preliminary evidence exists regarding the influence of ghrelin on the brain activity involved in processing external food cues." (PMID 35057485, 2022). "These peptides have been found to safely mimick the activity of leptin in mouse models of genetic and non-genetic obesity, diabetes, and cognitive impairment, thus overcoming the central and peripheral leptin resistance responsible for leptin’s failure in the clinic." (PMID 35527735, 2022). "The increased value of leptin in the tested obese horses may be another confirmation of the negative impact of obesity on the function of the cardiovascular system." (PMID 35327129, 2022). "Consistent with reduced obesity, HFD‐fed Cxxc5−/− mice exhibited markedly improved glucose tolerance and insulin sensitivity, with improved levels of metabolic parameters, including leptin, resistin, adiponectin, TGs, total cholesterol and HDL‐cholesterol levels." (PMID 35384342, 2022). "Despite its role and mechanisms of action not yet being fully understood, leptin may represent the answer to obesity and its related pathologies, including CRC, as a function of its genetic interference." (PMID 35563103, 2022). "There is also evidence showing elevated levels of proinflammatory adipokines (leptin) and decreased anti-inflammatory adipokines (adiponectin) in the GCF of obese patients with/without periodontitis, a direct reflection of the systemic changes of proinflammatory cytokine concentration in obesity." (PMID 35883424, 2022).
Obesity (continued). "In the CNS, leptin resistance means that, despite high leptin levels and large fat reserves, the brain does not receive signals to stop food intake and to expend more energy, resulting in a further increase in obesity through a sense of hunger and reduced energy expenditure." (PMID 35406000, 2022). "Indeed, endocrine dysfunction of the adipose tissue develops insulin resistance as the primary pathogenesis of metabolic syndromes: levels of leptin and adiponectin show positive and negative correlations, respectively, with obesity and severity of NAFLD." (PMID 36005486, 2022). "ASIC1a in OPC reveals calcium permeability, however whether it has a role in leptin signaling needs to be determined; therefore, future studies would need to specifically focus on ASIC1 in OPC in order to confirm its relationship with obesity." (PMID 35207041, 2022). "Counter-intuitively, since it is well-established that leptin induces satiety, stimulates lipid metabolism, and enhances energy expenditure, one would not expect hyperleptinemia to be part of the pathology of obesity, but rather a part of its resolution." (PMID 35527735, 2022). "Notably, some possible mediators of obesity‐related SNS activation have been suggested, such as adipokines (like leptin, angiotensinogen, interleukin‐6, and tumor necrosis factor‐α), angiotensin II, hyperinsulinemia, impaired baroreceptor reflexes, and activated chemoreceptor reflexes." (PMID 35739356, 2022). "Our previous study has proven that leptin/LepR signaling, an important adipocytokine signaling, could promote osteogenesis differentiation through STAT3 signaling pathway, which indicated the intrinsic interaction between obesity and OLF." (PMID 35712246, 2022). "Whereas leptin appears not to hold promise as a stand-alone therapy for the treatment of common obesity, its combination with pramlintide (Amylin Pharmaceuticals) induces greater body weight loss in individuals of excess weight relative to treatment with either drug alone." (PMID 34815532, 2022). "Interestingly, high-fat diets can induce precocious puberty independent of obesity and leptin levels." (PMID 36501034, 2022). "In summary, our results indicated that obesity might increase AA severity by favoring the expansion of Th17‐like and Th2/Th17 cells and decreasing regulatory CD4+T cell subsets, being adverse effects probably mediated by leptin overproduction." (PMID 35734271, 2022). "Leptin, fasting insulin, and ISI did not have significant genetic associations with endometriosis, PCOS, or UF after adjustment for obesity traits, nor did they have any associations with the obesity traits themselves." (PMID 35104295, 2022). "Interestingly, circulating leptin concentrations were negatively correlated with load to failure and poor histological structure of the repaired enthesis, suggesting a biochemical link between HFD/obesity and poor tendon outcomes." (PMID 35201374, 2022). "For that purpose, group of 45 children with obesity (OB) and group of 45 age‐matched children without obesity (CG) were examined in terms of serum levels of miR‐27a and biochemical parameters: fasting blood glucose, adiponectin, leptin, resistin, subfatin, visfatin, and TNF‐α, IL‐6." (PMID 34918493, 2022). "Therefore, increasing leptin levels via medications and/or nutritional strategies is not an effective strategy for treating obesity, but it can be a promising strategy for preventing it." (PMID 34928408, 2022). "Besides this controversy, the majority of the studies of leptin in children have been performed in populations with overweight and obesity where the sex influence usually is not analysed." (PMID 36064746, 2022). "The mechanism linking BMI and ATN is not too clear, however, it is suggested that obesity and insulin resistance increase thyroid stimulating hormone secretion via leptin signaling, ultimately resulting in the expansion of thyroid volume and formation of nodules." (PMID 35108333, 2022).
Obesity (continued). "Obesity-related metabolic disorders elicit systemic low-grade inflammation by increasing the levels of proinflammatory factors, such as monocyte chemoattractant protein-1 (MCP-1), CD11c, tumor necrosis factor-α (TNF-α), leptin, lipopolysaccharide binding protein (LBP), and interleukin-6 (IL-6)." (PMID 34579036, 2021). "We suggest that LEP/LEPR heterozygosity may dispose to overweight and obesity particularly in adulthood, and together with obesogenic factors, it may contribute to the development of obesity." (PMID 34448070, 2021). "However, our data indicate that inflammatory markers in ACE inhibitor-treated animals are lower prior to a reduction in leptin expression, suggesting that leptin is not the principal factor in inflammation in obesity and its reduction by ACE inhibition." (PMID 34149621, 2021). "Since the amount of adipose tissue is enlarged, overweight and obesity increase the secretion of nonesterified fatty acids and different hormones and cytokines, such as leptin, adiponectin and pro-inflammatory cytokines, which are associated with insulin resistance." (PMID 33037438, 2021). "In addition to it, there is an increased level of hormones like leptin, resistin, and cytokines in obese subjects compared to non-obese individuals, which cumulatively relates obesity to various co-morbidities." (PMID 33669862, 2021). "Some factors that might play a role in the interaction between asthma and OSA include local inflammation in the upper airway, allergic rhinitis, systemic inflammation, circulating leptin, neuromechanical reflex bronchoconstriction, intermittent hypoxia, GERD, obesity, and asthma therapy." (PMID 33510178, 2021). "In addition, leptin promotes T-cell proliferation and Th1/Th17 cytokine secretion such as IFN-γ, and prevents their apoptosis through the mTOR signalling pathway after antigen stimulation, maintaining chronic, obesity-related low-grade inflammation." (PMID 34199040, 2021). "The tumor-killing effector cells (CD8+ T) were suppressed and the immunosuppressor cells (MDSCs/M2) were over-activated to drive their recruitment and suppressive capacity, which could be mediated by obesity-related molecular markers, such as IL-6, CRP, leptin, IL-1β." (PMID 34350120, 2021). "However, PNS-induced modulation of gut microbiota has negative effects in leptin gene-deficient mice, suggesting that PNS’ obesity improving effects are inseparable from the interaction between intestinal flora and insulin." (PMID 34512356, 2021). "It is also not yet clear how AT neuropathy in obesity might affect sensory innervation or function, which may also contribute to central leptin response in addition to the neuroendocrine negative feedback loop of leptin action." (PMID 34613819, 2021). "In conclusion, we suggest that serum leptin can identify NAFLD without obesity as a confounding factor, whereas adiponectin combined with specific serum lipids might be advantageous for NAFL vs. NASH stratification." (PMID 34249975, 2021). "Notably, circulating levels of leptin were increased in HFD-fed mice compared to LFD-fed mice with no alterations in leptin receptor hypothalamic expression, suggesting no alterations in leptin sensitivity, as has been previously reported in obesity." (PMID 33349590, 2021). "PTP1B overexpression is strictly related to insulin resistance, whereas PTP1B inhibition or genetic ablation improve glucose homeostasis, cellular sensitivity to both insulin and leptin, and resistance to diet-induced obesity, without inducing hypoglycaemia or toxic effects." (PMID 34677434, 2021). "The development of treatment strategies to circumvent this problem may offer attractive opportunities for pharmaceutical intervention in the pathogenesis of obesity, which is the subject of our other study using MTS-leptin—a modified leptin with improved permeation across the BBB." (PMID 34438908, 2021). "Obesity is thus the result of hypercaloric ingestion and lack of leptin signaling." (PMID 33937257, 2021).
Obesity (continued). "However, some obese individuals do not have a shortage of leptin, on the contrary their obesity is often related to the phenomenon of “leptin resistance”." (PMID 34638947, 2021). "The elevated leptin disrupted epithelial polarity and promoted premalignant alterations of the mammary gland in obese mice involving the activation of the PI3K/Akt pathway, providing a molecular basis for early alterations in epithelial architecture during obesity-mediated cancer initiation." (PMID 34350120, 2021). "Thus, enhanced leptin sensitivity is not mediating the diminished phagic drive in response to GABA-T knockdown in obesity." (PMID 34192532, 2021). "Therefore, we hypothesized that in children and adolescents age and gender may interact with the degree of obesity in the regulation of REE and that REE may be influenced by leptin." (PMID 33917063, 2021). "As such, simple assays including leptin, fibrinogen and hs-CRP levels might be able substitutes for the burdensome test performed on a cycle ergometer and may provide reliable data concerning CRF to the pediatric obesity management team." (PMID 33669882, 2021). "Thus, a metabolite that may be related to leptin and regional fat distribution, i.e., SFA, was strongly correlated with obesity according to metabolic status." (PMID 34099056, 2021). "However, in both ob/ob and db/db models the lack of leptin-driven satiety cues results in hyperphagia and obesity, which complicates data interpretation." (PMID 33804765, 2021). "The characteristic profile of soluble factors in obesity and aging, such as decreased adiponectin, elevated levels of C-reactive protein (CRP), leptin, tumor necrosis factor-α (TNF-α), and interleukin 6 (IL-6), could lead to progressive loss of muscle mass and an increase in fat mass." (PMID 34676021, 2021). "However, the effects of leptin on several neural circuits, including the SNA, require further investigations in order to obtain a more complete picture of the mechanisms involved in the pathogenesis of obesity and its complications." (PMID 34068919, 2021). "This leads to the concept that central leptin resistance may account for lack of hypothalamic regulation of food intake and energy expenditure as well as metabolic dysfunction, attributing to obesity, diabetes and other metabolic defects in hyperleptinemia." (PMID 34064112, 2021). "Moreover, mechanistic studies demonstrated that the deletion of the expression of BBS proteins, but not Ift88, impaired LepRb trafficking to the plasma membrane, leading to central leptin resistance in a manner independent of obesity." (PMID 34211092, 2021). "However, in the context of obesity where elevated levels of leptin are found, there is little evidence on the role of autophagy in breast cancer progression." (PMID 33763424, 2021). "In leptin transgenic TET-ON mice, oral doxycycline (DOX) causes leptin overexpression in proportion to the concentration of DOX, allowing for the transient elevation of leptin without increasing fat mass and consequently avoiding any obesity co-morbidities." (PMID 34955895, 2021). "Therefore, increased endocannabinoid levels in the hypothalamus in genetically obese animals would suggest that these mediators contribute to hyperphagia and obesity due to lack of leptin or of its action." (PMID 34718828, 2021). "Also, Leptin and TNF-α are involved in the pathogenesis of obesity and insulin resistance." (PMID 34039404, 2021). "Discrepancy between leptin mRNA and food consumption by M-LB/CS suggests that M-LB/CS may attenuate obesity via activating peripheral lipid catabolism (e.g., restoration of adiponectin mRNA and modulation of PPARs) without affecting central leptin resistance." (PMID 34943118, 2021). "They concluded that obesity could alter the ASCs phenotype to confer undesired RT resistance via enhanced secretion of leptin by ASCs, promoted the production of IL-6, and activated Notch pathways in these BC cells." (PMID 34350120, 2021).
Obesity (continued). "Third, because we used secondary data from KNHANES, we could not evaluate the levels of obesity-related hormones, such as insulin, estrogens, androgens, growth hormone, and leptin, which regulate adipose tissue distribution, metabolism, and appetite." (PMID 34836286, 2021). "In addition to leptin promoting profibrogenic responses via TGF-β signaling, obesity-induced leptin exacerbates NASH via enhancing the responsiveness to endotoxins, suggesting that leptin plays a key role in proinflammatory, profibrogenic processes involved in the progression of NAFLD." (PMID 33923817, 2021). "The lack of responsiveness of obese mice to leptin might result from “cellular leptin resistance” characteristic to obesity." (PMID 33673387, 2021). "Furthermore, amplifying signals from PrlhNTS neurons attenuates food intake and obesity in mice lacking leptin or with attenuated melanocortin signaling." (PMID 34462445, 2021). "Although the contribution of obesity in patients with OSAS appears to be due to mechanical factors, evidences strongly support the key role of inflammatory cytokines with a pro-inflammatory signaling pathways, a reduced effectiveness of leptin action combined with high adipokine levels." (PMID 33669035, 2021). "Like adipocytes in obesity, CAAs secrete significantly higher levels of motility factors such as CCL2, CCL5, autotoxin (ATX), as well as proinflammatory cytokines such as IL-1β, IL-6, TNF-α, VEGF, insulin-like growth factor binding protein-2 (IGFBP-2), and leptin but much less of adiponectin." (PMID 33916703, 2021). "Today, leptin sensitizers rather than leptin itself are expected to be anti-obesity drugs." (PMID 34489483, 2021). "Moreover, obesity is a prevalent manifestation of metabolic disorders, and accumulating evidence has demonstrated that TC, TG, LDL-C, INS, and LEP levels were significantly higher in obese than in normal weight people, while the concentrations of ADP and ghrelin decreased." (PMID 33585429, 2021). "Thus, SOCS3 upregulation and altered systemic leptin levels could be responsible for the reduced IFN-I response as well as for other immune dysfunctions relevant to T and B cells in people with obesity." (PMID 33430520, 2021). "Clinical studies have found that acupuncture is widely used in the clinical treatment of obesity in recent years, but whether it can improve leptin resistance has not been systematically reviewed." (PMID 34260523, 2021). "In support of this, these authors showed that an acute treatment with a PPARβ/δ agonist GW501516 depletes WAT lipid accumulation in these genetically obese mice, suggesting that the anti-obesity actions of PPARβ/δ are not dependent on leptin signaling pathways." (PMID 33924880, 2021). "However, obesity leads to chronic inflammation in the body, and matrix metalloproteinase‐2 (MMP2), which is activated by nuclear factor kappa B (NF‐κB) in hypothalamic cells, induces leptin resistance by cleaving hypothalamic leptin receptors." (PMID 33830560, 2021). "In this respect, leptin, the main hormone playing an important role in the regulation of food intake and body weight, is increased in patients with migraine (i.e., migraine with and without aura) and obesity." (PMID 34177788, 2021). "Moreover, excess STAT3 activity inhibited POMC expression in the hypothalamus of diet-induced obesity mice, implying that STAT3 inhibition may promote leptin signaling." (PMID 34944525, 2021). "In addition, leptin concentrations rise in both humans and animals parallel with the rise in obesity, a clear demonstration that this hormone does not operate as a weight-normalizing negative-feedback signal." (PMID 34836068, 2021). "However, recent studies using fluorescently labelled leptin, suggests that the transport of leptin into the brain is not affected by dietary-induced obesity." (PMID 33679451, 2021). "We hypothesized that systemic blockade of leptin signaling will treat hypertension in NZO mice without exacerbating obesity and SDB." (PMID 34276408, 2021).